CD274 (CD274 molecule)
Diseases named in the same sentence as CD274 in open-access papers (continued):
Sharing a sentence is not in itself a finding about the gene and the disease.
melanoma (continued). "Indeed, entinostat-treated B16-F10 melanoma cells grew faster, an effect reversed on Cd274 (PD-L1 gene) knockdown using CRISPR." (PMID 34753889, 2022). "Although PD-L1 positivity by IHC has limited predictive value for objective response classification in patients with melanoma, elevated levels of CD274 mRNA at baseline might explain, to some degree, durable responses to PD-1-based immunotherapies." (PMID 36522538, 2022). "A. PTPN11 mRNA expression weakly associated with reduced CD274 mRNA expression in melanoma tumors regardless of ICI exposure." (PMID 34437586, 2021). "CD274 expression in melanoma tissues is typically stimulated by immune infiltrates rather than an intrinsic mechanism, therefore we used the significantly differentially expressed genes that were found in the PD-L1CON cell lines as a surrogate for PD-L1CON expression." (PMID 34503064, 2021). "Furthermore, we identified POU2F2, IRF1, and FOSL2 as the most highly correlated TFs with CD274 expression in melanoma across all five datasets." (PMID 34503064, 2021). "Similarly, low expression of SAMD9L, positively correlated with CD274, was beneficial for lymphoma patients, whereas high expression of the same gene was beneficial for melanoma and breast cancer patients." (PMID 34067485, 2021). "Small-cell lung cancer, squamous cell carcinoma of the oral cavity, cervical cancer, ovarian cancer, breast cancer, melanoma, bladder cancer, head and neck cancer, soft tissue sarcoma and prostate cancer exhibit increased copy number of chromosome 9p24, on which CD274 resides." (PMID 30283733, 2018). "Evaluation of melanoma data from The Cancer Genome Atlas (TCGA) revealed strong positive correlations between PDPN expression and several immune checkpoint receptors, including PD-L1, CTLA4, LAG3, TIGIT, and BTLA, with the association with PD-L1 (CD274) being the most prominent (r=0.504, p<0.001)." (PMID 41573582, 2025). "A study analyzing 95 melanoma patients treated with ICIs found that genes affected by VARs associated with hypophysitis include SMAD3, PRDM1, and IL1RN, while genes affected by CNVs related to the occurrence of hypophysitis are TERT, SMAD3, JAK2, PRDM1, FAN1, CD274, and UNG." (PMID 41465179, 2025). "Enhanced IFNγ gene signature (IFNγ, CD274, LAG3, CXCL9) is associated with higher overall response rates and longer median progression-free survival among metastasized non-small cell lung carcinoma, urothelial cancer or melanoma patients receiving PD-1 inhibitors or anti-PD-L1 antibodies." (PMID 37671945, 2023). "Therefore, activated anti-tumor immunity, high PDCD1, CD274, and CTLA-4 expression, and enhanced tumor immunogenicity might explain why the low-risk melanoma patients were found to be more likely to benefit from ICI treatment than the high-risk patients." (PMID 37620409, 2023). "Additionally, the discrepancy in the miRNA correlation detected could possibly indicate changes in the melanoma cells themselves as well as in the immune infiltrate within the TME that could be connected to the CD274 expression." (PMID 35802807, 2022). "Furthermore, the expression of ICIs between high- and low-risk melanoma patients were analyzed, indicating that the expression of immune-regulatory proteins (IRPs) such as PD-1 (PDCD1), PD-L1 (CD274), CTLA-4, HAVCR2 (TIM3), CD8, and LAG3 was significantly lower in the high-risk group (p < 0.05)." (PMID 35326741, 2022). "In addition, among the genes indirectly regulated by miR-146a through NFkB activity, we found CCL2, IL6, and VEGFA, which contribute to the proinflammatory phenotype, CD274 (PDL1), which promotes melanoma cell proliferation, and BCL2L1 and MCL1 antiapoptotic genes." (PMID 32967672, 2020).
melanoma (continued). "In this study, we found that ETV4 upregulates PD-L1 transcription in melanoma, consistent with prior findings in liver cancer where ETV4 binds the CD274 promoter, with the −734 to −339 bp region being essential for transcriptional regulation." (PMID 41502516, 2025). "The performance of PSMB9 in the melanoma cohort was comparable to that of previously reported signatures such as T cell-inflamed GEP, TAM M2, IFNG, CD8, and CD274, which all showed an AUC more than 0.8." (PMID 41020834, 2025). "Nevertheless, E2F1-induced expression of IL6 and CD274, or elevated levels of STAT3, can mitigate the effect nurturing toward the Th2 direction in advanced stages of melanoma." (PMID 39544930, 2024). "Consistent with the phenotype of CD163+ TAMs in the melanoma TME, moTAMs expressed the genes involved in immune suppression, including CD274 (PD-L1), PDCD1LG2 (PD-L2), and TGFB1." (PMID 38903497, 2024). "Remarkably, also mRNA expressions of CD274/PD-L1 and PDCD1/PD-1 were significantly down-regulated in pDCs exposed to melanoma secretome suggesting that pDCs become hyporesponsive to TLR-mediated stimulation when exposed to CM secretome." (PMID 38239354, 2023). "Among them, the PD-L1 (CD274) gene expression level is a validated biomarker for anti-PD-1 monotherapy and anti-PD-1 + anti-CTLA-4 in advanced melanoma." (PMID 37055772, 2023). "We found that its prediction performance is good in lung cancers and melanoma and is comparable to TMB, MSI, CD274, and TIDE scores in gastric cancer, ccRCC, glioblastoma, and metastatic urothelial cancer." (PMID 36497434, 2022). "A subpopulation with high HIF1α expression not only showed significantly higher expression of the canonical HIF1 target BNIP3L, but also of PD-L1 (CD274), as compared to a melanoma subpopulation with low HIF1α expression." (PMID 34268602, 2022). "Compared with TIDE, MIS score, CD274, CD8, IFNG, T.Clonality, B.Clonality, and Merck18, DDX20 alone had a higher AUC (0.62) in melanoma (Riaz2017_PD1_Mealnoma_lpi.Navie)." (PMID 36246406, 2022). "Compared with TIDE, MSI score, CD274, CD8, IFNG, and Merck18, DDX20 alone had a higher AUC (0.68) in melanoma (Liu2019_PD1_Mealnoma_lip_Naive)." (PMID 36246406, 2022). "For example, the well-known immune checkpoint inhibitor pembrolizumab is used to treat various types of cancer, including melanoma and triple-negative breast cancer (TNBC), as it targets PD-1 (PDCD1) and interferes with PD-L1 (CD274) interaction." (PMID 35651625, 2022). "Our screen identifies four candidate genes (CD274 (PD-L1), MCL1, JUNB, and B3GNT2) that, upon upregulation, enable human melanoma cells to evade T cell killing in diverse cancer cell types and mouse xenografts." (PMID 35338135, 2022). "In melanoma cells, the activated NRAS-RAF-MEK1/2-ERK-c-Jun axis enhanced the transcription of CD274." (PMID 33413496, 2021). "PD-L1 and PD-L2 cell surface expression were significantly correlated with the CD274 (PD-L1) and PDCD1LG2 (PD-L2) transcript expression in the nine melanoma cell lines with matched transcriptome data." (PMID 34073253, 2021). "Over the entire cohort, melanoma-specific survival (MSS) was influenced by CD2, PDL1 (CD274), and MITF (p = 0.01, p = 0.003, p = 0.03, respectively)." (PMID 33003444, 2020). "To assess the mRNA expression of four immunotherapy markers, CD274, PDCD1LG2, CD8A and IRF1, we used a multiplex RT-qPCR immunotherapy panel on the GeneXpert platform in melanoma patients treated with anti-PD-1 therapy." (PMID 31533832, 2019). "Immune checkpoint protein inhibitors, such antibodies against PD-L1 (aka CD274) and PD-1 (aka PDCD1), have shown effectiveness against a large number of cancer types, including melanoma, non-small-cell lung cancer, and renal cancer." (PMID 30951669, 2019). "Other metabolites produced by specific species of microbes can modify the activity of therapeutic agents, including PD-1 (PDCD1)/PD-L1 (CD274) targeting immunotherapies, in melanomas and other tumor types." (PMID 29945886, 2018).
melanoma (continued). "Moreover, we demonstrated that tumor ETV4 expression influences the crosstalk with infiltrating immune cells within the melanoma TME and affects the response to anti-PD-1 therapy, potentially due to its role in transcriptionally activating CD274 expression." (PMID 41502516, 2025). "Moreover, we examined the correlation between CTHRC1 expression and immunotherapy markers, including CD274, PDCD1, CTLA4, and LAG3 in colon cancer, thyroid cancer, and melanoma." (PMID 39052013, 2024). "CD274, PDCD1, CTLA4, and LAG3 were significantly positively correlated with CTHRC1 expression in colon cancer and thyroid cancer; while only CTLA4 was significantly positively correlated with CTHRC1 expression in melanoma." (PMID 39052013, 2024). "Additionally, the AUC for KIF20A in predicting response to PD-1 inhibitors was higher than for CD274 and PDCD1, a finding confirmed in another cohort of 28 melanoma patients undergoing anti-PD-1 checkpoint inhibition therapy." (PMID 39555078, 2024). "In a NSCLC, melanoma, and glioblastoma cohort, TxflSig exhibited superiority to several effective ICB biomarkers in predicting response to ICB treatments, including TIDE, MSI.score (microsatellite instability), CD274 (PD-L1), CD8, and INFG (INFγ)." (PMID 37835514, 2023). "Furthermore, our analysis revealed that within B16F10 melanomas HAVCR2 and LAG3 better characterize the development of a dysfunctional CTL phenotype than does the PDCD1/CD274 axis." (PMID 37182110, 2023). "Moreover, in stage IV melanoma patients with brain metastases, CCL18, CCR1, CCR4, CD274, CSF2, EGF, and PTGS2 genes were significantly over-expressed (p < 0.001, versus patients without melanoma brain metastasis)." (PMID 37091783, 2023). "Considering that CYTL1 may be a potential oncogene in melanoma, it was assessed how CYTL1 interacted with PDCD1, CD274, HAVCR2, TIGIT, SIGLEC15, CTLA4, LAG3, and PDCD1LG2." (PMID 37745303, 2023). "In addition, the mRNA abundance of PARP14 in both melanoma cells and patient samples (TCGA SKCM) positively correlated with that of STAT1, IFNG, and CD274." (PMID 37752135, 2023). "Their low expression of antigen presentation related genes (CD80 and CD274) and the absence of T cells at the earliest stage of melanoma regression support a T-cell independent action of macrophages on tumor cells." (PMID 37526660, 2023). "In this study, we take a systems biology approach to compare the importance of cytolytic versus IFNG-mediated cytostatic effects in a murine melanoma model (B16F10) and to dissect the contribution of immune checkpoints HAVCR2, LAG3, and PDCD1/CD274 to CTL exhaustion." (PMID 37182110, 2023). "Despite some correlations were found in all patients regardless of their CD274 status, CD274+ melanoma lesions showed a stronger correlation between miR‐186 and miR‐155/miR‐181b, while miR‐29a and miR‐17 were more strongly correlated in CD274– patients." (PMID 35802807, 2022). "Based on these data the melanoma cell line IRNE was chosen for miTRAP analysis, since it showed a low surface expression of CD274 despite high mRNA levels (data not shown), indicative of a posttranscriptional regulation of CD274." (PMID 35802807, 2022). "Detailed analysis of tumor-infiltrating myeloid cells from melanoma patients revealed that the CD206+ Macro_C1QC subset also expressed high levels of HLA-A (MHC I) and CD86, as well as ICOSLG, and low levels of CD274, as we had observed in our cross-presenting CD206+ M2a macrophages." (PMID 35503656, 2022). "Importantly, in the correlation analyses in human cancer patients by data mining of TCGA database, there were positive correlations among CD11C, CD274, CSF1R, and IFNG expression in lung adenocarcinoma, lung squamous carcinoma, and melanoma." (PMID 35917184, 2022). "CD274, also known as PD-L1, can bind to PDCD1 to downregulate T cell function in melanoma." (PMID 36704353, 2022).
melanoma (continued). "By comparing the miRNA expression pattern with CD274 positivity, a slightly lower expression of miR‐29a and miR‐181b was detected on CD274+ melanoma samples, but these differences were not statistically significant." (PMID 35802807, 2022). "Indeed, entinostat-treated B16–F10 melanoma cells grew faster in vivo, an effect reversed by CRISPR-mediated Cd274 (Pdl1) knockout using CRISPR or anti-PD1 treatment." (PMID 34453044, 2021). "Other cancer/drug histology differences reflected expected patterns; for example, CD274 (PD-L1) was significant in melanoma anti-PD-1 cohorts, but not anti-CTLA-4." (PMID 33508232, 2021). "PD-L1 (programmed death-ligand 1, B7-H1, CD274), the ligand for PD-1 inhibitory receptor, is expressed on various tumors, and its expression is correlated with a poor prognosis in melanoma." (PMID 33809167, 2021). "From the three studies, we hypothesize that the activity of SHP-2, rather than the expression, likely controls the expression of PD-L1 as only a weak relationship between PTPN11 and CD274 expression in either lung adenocarcinomas or melanomas was observed." (PMID 34437586, 2021). "Whereas a negligible PD-L1/CD274 expression of blood pDC and mDC of healthy donors has been described, blood DC of lung cancer patients show a clear PD-L1/CD274 expression in this study, thereby confirming the data of blood DC in patients with ovarian cancer and melanoma." (PMID 33066260, 2020). "PD-L1, also known as B7-H1 and CD274, is a type I transmembrane glycoprotein, which is expressed on antigen-presenting cells and some tumor cells, including melanoma, ovarian, and lung cancer cells." (PMID 29556567, 2018). "In addition to well-established IFNγ target genes such as CD274, IRF1, and B2M, three members of the PARP family—PARP9, −12 and −14—were consistently upregulated in all cell models as well as in IFNGhigh patient melanoma (comparing top 15% by IFNG expression to lowest 15% in the TCGA SKCM dataset)." (PMID 37752135, 2023). "In addition to targeting CD279, there are ongoing phase 1 clinical trials investigating the role of CD279 ligands: CD274/programmed death ligand (PD-L)-1 in patients with solid tumors [ClinicalTrials.gov:NCT00729664] and CD273/PD-L2 in stage IV melanoma patients [ClinicalTrials.gov:NCT00658892]." (PMID 25606596, 2014). "A similar result was obtained in urothelial, melanoma, and non-small cell lung carcinoma in which IFN-γ signaling-related genes, including IFNG, CD274, LAG3, and CXCL9, could well predict about who could benefit from the immunotherapy via anti-PD-L1/PD-1 antibody." (PMID 37637034, 2023).
lung cancer (2,674 papers, 2012 to 2026). A malignant neoplasm involving the lung. "On average, CD274 mutations are found in 0.96% of all cancers; the most common types are breast cancer, gastric cancer, lung cancer, colon cancer, bladder cancer, and prostate cancer." (PMID 36251702, 2022). "H3K18 lactylation activated POM121, which enhanced MYC nuclear translocation and direct binding to the CD274 to potentiate PD-L1 expression and finally potentiates immune escape of lung cancer." (PMID 40535811, 2025). "Unexpectedly, the inhibition of PRMT5 in lung cancer increases CD274 gene expression, eventually activating the PD1/PD-L1 axis and blocking T-cell-mediated antitumor immunity." (PMID 37394580, 2023). "Among these molecules, the level of CD274 gene, which encodes PD‐L1, was consistently elevated in all tumor cells, including the ovarian cancer cell line SKOV3, the lung cancer cell line A549, and the glioma cell line U87MG." (PMID 37009412, 2023). "The results showed that in EGFR mutation-positive lung cancer, not only the density and function of CD8+ tumor-infiltrating lymphocytes are suppressed, the PD-L1 genes CD274 and CD86 are also downregulated, and HHLA2 and VTCN1 (B7-H4) were upregulated." (PMID 36910653, 2023). "We also suggested that upregulation of CD274 inhibited proliferation and invasion of A549 cells and increased apoptosis in lung cancer cells." (PMID 36959799, 2023). "The lncRNAs NKX2-1-AS1—located in the 14q13.3 chromosome region—and NKX2-1 protein (also known as thyroid transcription factor 1, TTF-1) are co-expressed in lung cancer, although they have distinct effects on CD274 gene (encoding PD-L1)." (PMID 36612180, 2022). "Programmed death‐ligand‐1 (PD‐L1), is encoded by the CD274 gene and is a crucial immune checkpoint molecule that mediates the interaction between lung cancer cells and tumor‐infiltrating T cells." (PMID 35975458, 2022). "Amongst the differences in CD274-regulating TFs between cancer types, especially lung cancer stands out." (PMID 35289334, 2022). "The survival analysis using the TCGA lung cancer subset from Kaplan–Meier plotter showed that high CHRNΑ5 or CD274 expression correlated with poor prognosis, especially in lung adenocarcinoma, but not in lung squamous cell carcinoma (LUSC)." (PMID 35971127, 2022). "Immunotherapy regimes targeting the immune checkpoint molecules programmed cell death protein 1 (PD-1) and programmed death-ligand 1 (PD-L1, CD274) are showing great promises in treating lung cancers, especially in patients with pretreated advanced NSCLC." (PMID 34240739, 2021). "The aim of this study was to investigate the expression of the coinhibitory molecule PD-L1/CD274 in monocytes and dendritic cells (DC) in the blood of lung cancer patients undergoing PD1 inhibitor therapy and to correlate data with patient’s outcome." (PMID 33066260, 2020). "The transcriptional enhancer factor 1 (TEF-1) is a downstream effector of the Hippo pathway and also directly binds the CD274 promoter enhancing PD-L1 expression in lung cancer cell lines." (PMID 33114576, 2020). "Our results implicate that a high PD-L1/CD274 expression of blood monocytes and DC subtypes is a risk factor for therapy response and for the survival of lung cancer patients undergoing PD1 inhibitor therapy." (PMID 33066260, 2020). "Based on the analysis of the mRNA microarray, we observed that in lung cancer cells, miR-197 regulated the expression of PD-L1 (CD274, B7-H1), a member of the B7 family of costimulatory/coinhibitory ligands expressed in various tissues." (PMID 25597412, 2015). "In contrast, the PDL1 transcript, CD274 was higher in normal tissues than in lung cancer tissues." (PMID 38182561, 2024). "Based on these in silico data, we hypothesized that the CD274 promoter region of lung cancer cells is a potential target of the FOXM1 TF." (PMID 35975458, 2022). "Targeting PRMT5 reduced this inhibitory effect and promoted CD274 expression in lung cancer." (PMID 35111150, 2021).